INS (insulin)
Diseases named in the same sentence as INS in open-access papers (continued):
Sharing a sentence is not in itself a finding about the gene and the disease.
Insulin resistance (continued). "The functional changes in the skeletal muscle induced by defective insulin action, observed in the prediabetic state, are suggested to be associated with impaired muscle functional capacity, which in turn may exacerbate insulin resistance and promote the development of T2DM." (PMID 38612885, 2024). "Insulin sensitivity may be affected by adipokines (inflammatory molecules secreted by AT) in various tissues, particularly skeletal muscle and liver, by causing inflammation in the adipose tissue and contributing to whole body insulin resistance." (PMID 38632599, 2024). "Our results are consistent with findings reporting that insulin resistance during obesity is driven by an inflammatory response caused by the infiltration of adipose tissue by monocytes and other leukocytes, leading to disrupted insulin signalling and hyperglycaemia." (PMID 38999869, 2024). "Furthermore, insulin resistance is associated with dyslipidemia, creating a reciprocal relationship in which each condition has the potential to exacerbate the other, thereby necessitating mainly the administration of higher insulin doses." (PMID 39208059, 2024). "Similarly, in our study, excess iodate caused high insulin levels and a decrease in IR, which correlates with other studies that show that low levels insulin levels and low levels of IR are associated with pancreatic fibrosis, insulin resistance, and alterations in insulin gene regulation." (PMID 39056661, 2024). "Furthermore, Akoumianakis and colleagues observed that insulin treatment induces oxidative stress and endothelial dysfunction in the vessels of diabetic patients with atherosclerosis, which appears to be associated with insulin resistance." (PMID 38892513, 2024). "The molecular determinants underlying insulin resistance in these states include both cell-autonomous factors, such as genetics and epigenetics, and effects of extrinsic circulating factors, including lipids, cytokines, and miRNAs, that can modify insulin action." (PMID 38032738, 2024). "Decreasing sleep duration significantly reduced insulin sensitivity in healthy individuals, and sleep loss is a risk factor for insulin resistance and type 2 diabetes in humans, suggesting insulin-mediated metabolic changes could have impact on sleep regulation." (PMID 38324048, 2024). "This suggests that dysregulated insulin signaling could be the predisposing factor leading to the inhibition of the Sirt1-Pgc1a-Ucp2 axis, adipocyte dysfunction, and the eventual development of obesity and insulin resistance with age." (PMID 38891115, 2024). "Furthermore, recent evidence suggests that physical activity may improve insulin sensitivity and reduce the risk of insulin resistance‐related complications, such as T2D." (PMID 37938877, 2024). "Second, since insulin resistance and impaired insulin secretion are important mechanisms underlying cardiovascular disease morbidity and mortality, raw vegetables may increase insulin sensitivity and stimulate insulin secretion." (PMID 39262431, 2024). "GI and glycemic load (GL) are relevant in the management of GDM because diets rich in GI and GL may induce or exacerbate insulin resistance, whereas a low-GI diet is associated with improved glycemic control, reduced insulin requirements, lower cholesterol levels, and decreased inflammation." (PMID 39389786, 2024). "In the scientific literature, it has been well highlighted that the increased circulating levels of insulin, associated with conditions of insulin resistance, are responsible for progressive cardiovascular alterations over the years that could stimulate the development and/or the worsening of HFpEF." (PMID 38672161, 2024). "Numerous studies have observed the impact of abundant accumulation of lipids on insulin signaling in the liver and muscle, concentrating on the downregulation of surface insulin receptors and the damaged transduction of insulin signals in insulin resistance associated with obesity." (PMID 39807459, 2024).
Insulin resistance (continued). "This disruption affects insulin and lipid metabolism, along with immune-related pathways; promotes the synthesis of free fatty acids; and causes lipid deposition in the liver, thus leading to insulin resistance and lipid metabolism disorders, then inflammation and oxidative stress." (PMID 39599662, 2024). "However, the blood ketone concentrations were inversely associated with insulin resistance, implying that increased ketone production from KD ingestion might improve insulin action." (PMID 38198459, 2024). "However, reverse causality in the background cannot be excluded, mainly in the case of cancer of the pancreas, which may directly damage insulin-secreting beta cells and impair their function or induce peripheral insulin resistance, thereby causing DM." (PMID 38730697, 2024). "In addition, some insulin‐signaling proteins, such as p70S6K, p‐GSK3β, p‐Akt, and p‐insulin receptor, are contained in serum sEVs, indicating its association with incidences of insulin resistance." (PMID 37593852, 2023). "Therefore, improved insulin metabolism by Vitamin D supplementation may decrease the risk of metabolic complications related to insulin resistance." (PMID 37689713, 2023). "Also, SOCS1 has been shown to down-regulate insulin signaling and cause insulin resistance." (PMID 36609306, 2023). "The FFAs exert lipotoxic effects that contribute to hepatic damage by impairing insulin production in pancreatic β‐cells and exacerbating hepatic oxidative activity, mainly depending on reactive oxygen species (ROS) generation associated with hyperglycemia and insulin resistance." (PMID 37823118, 2023). "A study showed that patients with HUA are at significantly higher risk of developing insulin resistance, and that elevated UA leading to insulin resistance may be related to the ability of high UA to increase insulin secretion in all temporal phases of pancreatic β-cells." (PMID 37818085, 2023). "Furthermore, glucose is disposed primarily in the skeletal muscle in an insulin-responsive manner, and the loss of muscle mass may lead to insulin resistance." (PMID 37656239, 2023). "Likewise, other mechanisms by which insulin resistance contributes to the appearance of elevated blood pressure in the metabolic syndrome are the loss of the vasodilator effect of insulin, vasoconstriction caused by free fatty acids, and sympathetic hyperactivation." (PMID 36677012, 2023). "Second, elevated HCY could either impair insulin secretion through alterations in beta-cell glucose metabolism and generation of key stimulus-secretion coupling factors, or induce insulin resistance and cause diabetic phenotypes by protein cysteine-homocysteinylation of the pro-insulin receptor." (PMID 37322514, 2023). "In our study, while Zfyve28 liver-specific overexpression in mice impaired insulin sensitivity and caused an increase in lipid content in the serum and liver, Zfyve28 liver-specific knockout in mice significantly improved insulin sensitivity and other indicators associated with insulin resistance." (PMID 37884540, 2023). "While Zfyve28 liver-specific overexpression in mice impairs insulin sensitivity and causes an increase in lipid content in the serum and liver, Zfyve28 liver-specific knockout significantly improves insulin sensitivity and relevant indicators associated with insulin resistance." (PMID 37884540, 2023). "In addition, BCAAs can continuously activate mTOR signal and damage insulin signal transduction through insulin receptor substrate, and abnormal BCAAs metabolism can cause the accumulation of BCAAs metabolites and eventually lead to insulin resistance." (PMID 36824437, 2023). "Importantly, Akkermansia is associated with lower insulin sensitivity in patients with insulin resistance, and the Firmicutes-to-Bacteroidetes ratio can be elevated, with a decrease in the number of butyrate-producing bacteria, including Roseburia or Faecalibacterium prausnitzii." (PMID 37515062, 2023).
Insulin resistance (continued). "Insulin resistance is closely associated with cardiovascular disease and can cause myocardial fibrosis and myocardial injury and even induce cardiac insufficiency through abnormal insulin metabolism, mitochondrial dysfunction, hyperglycemia, and glucose toxicity." (PMID 37350790, 2023). "T1D is characterized by absolute insulin deficiency, typically of autoimmune origin, requiring lifelong insulin treatment while T2D is marked by relative insulin deficiency with insulin resistance and, at least initially, may respond to lifestyle or non-insulin agents." (PMID 37293006, 2023). "Likewise, elevated levels of ceramides of a certain chain length and saturation of fatty acids, which belong to sphingolipids, are reported to impair insulin sensitivity through reduced adiponectin and increased inflammation caused by insulin resistance initially." (PMID 37152942, 2023). "Moreover, the underlying mechanisms from NAFLD to PCOS might be linked via higher circulating levels of fasting insulin (a proxy of insulin resistance) and sex hormones (mainly bioavailable testosterone levels)." (PMID 36800955, 2023). "Considering that the main pathogenesis of type 2 DM is insulin resistance and impaired insulin secretion, we hypothesize that the increased risk of DM during long sleep duration may be due to the deterioration of pancreatic beta cell function caused by excessive sleepiness." (PMID 37109236, 2023). "Therefore, the metabolic disorders, including DKA may be caused by decreased insulin secretion due to severe insulin resistance and β-cell dysfunction." (PMID 37645409, 2023). "Moreover, sharp long-term changes in blood insulin levels in normal individuals may cause insulin resistance in organs and tissues, a central mark of hyperglycemia and type 2 diabetes." (PMID 36900596, 2023). "In TM patients, insulin resistance is caused by hepatic IO that interferes with the suppression of hepatic glucose production from insulin, and by iron deposition in the muscle that decreases the glucose uptake, while a reduced insulin secretion can be present also in normoglycemic patients." (PMID 37115218, 2023). "However, long-term statin use may reduce insulin sensitivity, increase insulin resistance, and increase the risk of NODM." (PMID 37369993, 2023). "Moreover, to check if systemic insulin resistance could also be associated with skeletal muscle insulin resistance, we verified if in vitro exposure of muscle pieces to insulin was able to activate AKT." (PMID 36978840, 2023). "However, whether insulin resistance causes liver steatosis or NAFLD causes insufficient insulin degradation to promote hyperinsulinemia and secondary insulin resistance is still under discussion." (PMID 36678603, 2023). "Plasma insulin level with its role in the atherosclerotic process constitutes an independent risk factor for cardiovascular diseases, which increases the importance of early detection of insulin resistance before cardiovascular diseases are clinically present, and of intervening." (PMID 36874319, 2023). "Therefore, high dietary selenium intake may increase NAFLD risk by dysregulating insulin biosynthesis and secretion and stimulating glucagon secretion, insulin resistance, and dyslipidemia." (PMID 36864425, 2023). "In type 1 diabetes (T1D), insulin secretion is rapidly lost due to autoimmune-selective β-cell destruction, whereas in type 2 diabetes (T2D), the delayed onset and gradual progression of insulin deficiency reflect exhausted β-cell efforts to compensate for insulin resistance." (PMID 38298268, 2023). "In GC isolated from the ovaries of women with PCOS, insulin action on glucose metabolism is significantly decreased, so the differences are probably linked to differing responses to insulin and/or connected with insulin resistance in obese PCOS GC, but this needs further study." (PMID 37658762, 2023).
Insulin resistance (continued). "Moreover, these oral antidiabetics could improve insulin resistance, thus implying a lower dose of insulin and therefore a lower risk of hypoglycemia." (PMID 38044455, 2023). "However, obesity is also linked to insulin resistance, impeding insulin response." (PMID 37526326, 2023). "Although the mechanisms responsible for the occurrence of this phenomenon are not yet well investigated, it appears that partial β-cell recovery with improved endogenous insulin production, transient recovery of immune tolerance and reduced peripheral insulin resistance may play an underlying role." (PMID 37180128, 2023). "However, when the capacity of mitochondrial oxidation exceeds, lipids are stored as TAGs and might be converted into lipid metabolites such as DAG, which is known to inhibit insulin signaling, thus causing insulin resistance." (PMID 37602323, 2023). "Thus, deficiencies in insulin-sensitive tissues, such as adipose tissue, pancreas, liver, and skeletal muscle, may trigger insulin resistance and type 2 diabetes in the offspring." (PMID 38068828, 2023). "However, very little information is available on whether BPA-induced insulin resistance is associated with an increase in insulin dosage or frequency of injections." (PMID 38132710, 2023). "In addition, for clinical practice, the interpretation of laboratory and anthropometric parameters could estimate with good approximation the level of insulin, highlighting also a possible underlying diagnosis of insulin resistance and/or hyperinsulinemia." (PMID 37754306, 2023). "Therefore, it can reduce insulin sensitivity and insulin resistance caused by obesity." (PMID 36788534, 2023). "Moreover, a decrease in waist circumference typically reflects a reduction in visceral fat, which is linked to insulin resistance, and thus, waist circumference reduction can lead to improved insulin sensitivity, making it easier for the body to utilize insulin effectively." (PMID 37960315, 2023). "In addition, galectin-3 has been implicated in metabolism and in insulin resistance; in patients with heart failure, especially heart failure with a reduced ejection fraction, there was a higher rate of insulin resistance than in the group with a preserved ejection fraction." (PMID 36673621, 2023). "In this line, Copenhagen Insulin and Metformin Therapy trial (n = 370 individuals) found that metformin therapy is associated with decreased amino acids, including valine, tyrosine, and carnitine serum levels associated with insulin resistance and mitochondrial dysfunction." (PMID 37510368, 2023). "Furthermore, growing insulin resistance and elevated insulin secretion from the pancreas could cause pancreatic beta-cell exhaustion." (PMID 37547304, 2023). "Visceral adipose tissue has been associated with insulin resistance and metabolic syndrome in adults and, compared to subcutaneous fat, visceral fat is related to a less favorable adipokyne and inflammatory profile, leading to a significant reduction in insulin sensitivity." (PMID 37342257, 2023). "In addition, almost all parameters associated with insulin resistance demonstrated significant improvements after the diet, including the levels of fasting insulin (p < 0.001), fasting glucose (p < 0.001) and HbA1c (p < 0.001), and mean HOMA-IR score (p < 0.001)." (PMID 37242145, 2023). "An improved understanding of physiological insulin signaling and cellular insulin resistance may pave the way for innovative therapeutic strategies against type 2 diabetes and other age-associated pathologies related to insulin resistance." (PMID 35768470, 2022). "For these reasons, it becomes important to separate the effects of insulin resistance from those of hyperinsulinemia because excess circulating insulin might cause overstimulation of tissues that are marginally involved in metabolism and have preserved sensitivity to insulin action." (PMID 36289636, 2022).
Insulin resistance (continued). "Insulin resistance has been previously associated with increased plasma levels of deoxycholic acid and its conjugated forms and increments in the ratio of unconjugated/conjugated BA were attributed to subjects with high plasma concentrations of insulin, NEFA, and triglyceride levels." (PMID 35774538, 2022). "In addition, insulin resistance is associated with hyperinsulinemia and hyperglycaemia due to impaired insulin signalling of those effects, increasing the amount of insulin and glucose in the circulation system and reducing the levels of glucose uptake and glycogen." (PMID 36235772, 2022). "Taken together, these studies imply that the low glutamine concentrations observed at timepoint 1 in the women who developed GDM might reflect both lower insulin secretion as well as increased insulin resistance and may be indicative of an underlying mechanism leading to GDM in this high-risk group." (PMID 36295825, 2022). "Stress hyperglycemia in the early phase was crucial to permanent hyperglycemia progression after AP, which might be explained by the insulin resistance induced by endothelial dysfunction and decreased insulin biosynthesis and secretion caused by oxidative stress." (PMID 35692404, 2022). "However, this possibility seems unlikely because it is generally appreciated that the effect of insulin on glucose metabolism is impaired earlier during the development of insulin resistance, and that only severe insulin resistance or deficiency impair its effect on lipolysis." (PMID 35163277, 2022). "Insulin resistance is multifactorial caused by genetic and environmental factors (predominantly obesity), and in a certain situation such as acute illness it may result in a reduced effect of the insulin action, which causes elevated glucose levels." (PMID 36435766, 2022). "In addition, as phytochemicals can increase the body’s production of insulin, the components of fruits and vegetables may play a role in preventing insulin resistance associated with MetS." (PMID 35468272, 2022). "(c) In subjects with T2DM, obesity, and insulin resistance, hypertriglyceridemia has been shown to be attributed to a defect in the postprandial dynamic adjustment of triglyceride clearance across the adipose tissue, caused by blunted insulin-stimulated rates of blood flow." (PMID 35683611, 2022). "Furthermore, phosphorylation at these residues on IR and IRS proteins reduces insulin signaling and may cause insulin resistance." (PMID 35682723, 2022). "Decreased insulin sensitivity and insulin resistance are associated with a high risk of cardiovascular disease, disturbed lipid, lipoprotein metabolism (Dyslipidemia), the subsequent overproduction of potentially atherogenic lipid and lipoproteins and development of insulin resistance." (PMID 35565871, 2022). "Thus, a comprehensive scrutiny of autophagy activation during disease progression and cardiac insulin resistance associated with plasma glucose and insulin levels could yield precise mechanistic relations." (PMID 36267813, 2022). "Decreased insulin sensitivity might be one component, it has been reported that inflammation and oxidative stress induced by obesity is linked to the development of local and systemic insulin resistance." (PMID 36564775, 2022). "Thus, less insulin degradation would be associated with systemic insulin resistance." (PMID 35163746, 2022). "Several data indicate that they may actually represent different effects with different mechanisms (e.g., pleiotropism), although it is possible that, for at least some of them, a pathogenic link mediated by abnormal insulin signaling and insulin resistance does actually exist." (PMID 35055114, 2022). "Another example is, while the sarcopenic obese phenotype is consistently insulin resistant due to obesity, the anorexic phenotype may be heterogeneous depending on whether the sarcopenia (which increases insulin resistance) or the weight loss (which increases insulin sensitivity) is dominant." (PMID 35723859, 2022).